FERMT2 (FERM domain containing kindlin 2)
Description:
Scaffolding protein that enhances integrin activation mediated by TLN1 and/or TLN2, but activates integrins only weakly by itself. Binds to membranes enriched in phosphoinositides. Enhances integrin-mediated cell adhesion onto the extracellular matrix and cell spreading; this requires both its ability to interact with integrins and with phospholipid membranes. Required for the assembly of focal adhesions. Participates in the connection between extracellular matrix adhesion sites and the actin cytoskeleton and also in the orchestration of actin assembly and cell shape modulation. Recruits FBLIM1 to focal adhesions. Plays a role in the TGFB1 and integrin signaling pathways. Stabilizes active CTNNB1 and plays a role in the regulation of transcription mediated by CTNNB1 and TCF7L2/TCF4 and in Wnt signaling.
Synonyms: MIG-2; KIND2; MIG2; PLEKHC1; UNC112B; UNC112
Tractability: Small molecule: a structure with a bound ligand is known. Antibody: its Gene Ontology location is reachable by antibodies, with high confidence; UniProt places it where antibodies can reach, with medium confidence. PROTAC: ubiquitination databases record sites on it; its protein half-life has been measured.
Gene: Protein-coding gene on chromosome 14 (52,857,267 to 52,952,435, reverse strand). Ensembl gene ENSG00000073712.
Subcellular location: Cytoplasm; Cytoplasm, cell cortex; Cytoplasm, cytoskeleton; Cytoplasm, cytoskeleton, stress fiber; Cell junction, focal adhesion; Membrane; Cell projection, lamellipodium membrane; Nucleus; Cytoplasm, myofibril, sarcomere, I band; Cell surface
Subcellular location (Human Protein Atlas): Focal adhesion sites; Cytosol; Nucleoplasm
Pathways (Reactome):
Signal Transduction: RAC1 GTPase cycle; RAC3 GTPase cycle
Cell-Cell communication: Cell-extracellular matrix interactions
Gene Ontology:
Molecular function: actin binding; phosphatidylinositol-3,4,5-trisphosphate binding; protein binding; protein kinase binding; protein serine/threonine kinase activator activity; protein serine/threonine kinase binding; SMAD binding; type I transforming growth factor beta receptor binding; integrin binding; actin filament binding
Biological process: adherens junction maintenance; cell adhesion; cell-matrix adhesion; focal adhesion assembly; integrin activation; integrin-mediated signaling pathway; negative regulation of fat cell differentiation; negative regulation of vascular permeability; positive regulation of cell migration; positive regulation of epithelial to mesenchymal transition; positive regulation of ERK1 and ERK2 cascade; positive regulation of focal adhesion assembly; positive regulation of integrin activation; positive regulation of mesenchymal stem cell proliferation; positive regulation of osteoblast differentiation; positive regulation of phosphatidylinositol 3-kinase/protein kinase B signal transduction; positive regulation of protein localization to nucleus; positive regulation of Rho protein signal transduction; positive regulation of stress fiber assembly; positive regulation of substrate adhesion-dependent cell spreading; positive regulation of wound healing, spreading of epidermal cells; protein localization to cell junction; regulation of cell morphogenesis; transforming growth factor beta receptor signaling pathway; Wnt signaling pathway; and 3 more
Cellular component: adherens junction; cell junction; cytoplasm; cytoplasmic side of plasma membrane; cytosol; focal adhesion; nucleoplasm; nucleus; plasma membrane; cell cortex; cell surface; cytoskeleton; I band; lamellipodium membrane; membrane; stress fiber
Genetic constraint (gnomAD): Loss-of-function variants: 10 observed, 55.86 expected, observed/expected ratio (o/e) 0.18, 90% interval 0.11 to 0.3. The upper end of that interval is the gene's LOEUF score, 0.3, which puts it in group 1 of 6, group 1 being the genes least tolerant of losing a copy. Missense variants: 511 observed, 674.93 expected, observed/expected ratio (o/e) 0.76, 90% interval 0.7 to 0.81. Synonymous variants: 221 observed, 233.11 expected, observed/expected ratio (o/e) 0.95, 90% interval 0.85 to 1.06.
Homologues: Orthologues: chimpanzee FERMT2 (100% identical), dog FERMT2 (99% identical), macaque FERMT2 (99% identical), pig FERMT2 (99% identical), guinea pig FERMT2 (99% identical), rat Fermt2 (99% identical), mouse Fermt2 (98% identical), rabbit FERMT2 (98% identical), tropical clawed frog fermt2 (95% identical), zebrafish fermt2 (91% identical), Drosophila melanogaster Fit1 (49% identical), Drosophila melanogaster Fit2 (46% identical), and 1 more. Paralogues in human: FERMT1 (63% identical), FERMT3 (53% identical).
Diseases named in the same sentence as FERMT2 in open-access papers:
FERMT2 is named in the same sentence as 110 diseases in open-access papers, as found by Europe PMC text mining. Sharing a sentence is not in itself a finding about the gene and the disease. The quoted sentences say what the papers report.
breast carcinoma (36 papers, 2010 to 2025). "On the other hand, FERMT2 has been linked to tumor pathogenesis and is highly expressed in multiple kinds of cancer, including gastric cancer, breast cancer, and glioblastoma multiforme." (PMID 36480537, 2022). "Over-expression of FERMT2 promotes tumor formation in breast cancer and was linked with poorer patient outcomes." (PMID 34771544, 2021). "FERMT2 (also known as Kindlin-2), a focal adhesion protein, has been found to regulate cancer cell proliferation, apoptosis, and chromosomal abnormalities in breast cancer that are associated with tumor stromal invasion, lymph node metastasis, and patient outcome in gastric cancer." (PMID 34771544, 2021). "In breast cancer, FERMT2 regulates tumor growth through promoting CSF-1-mediated infiltration of macrophages." (PMID 36480537, 2022). "Studies of breast cancer cells revealed a further role for FERMT2 in controlling EMT by interacting with DNMT3A and promoting CpG methylation of both clusters’ promoters." (PMID 34884985, 2021). "TGF-β1 signaling is elevated in anoikis-resistant breast cancer cells, and FERMT2 knockdown reduces TβRI expression, suggesting FERMT2 may regulate AR through the TGF-β1 pathway." (PMID 40024947, 2025). "Previous studies showed that FERMT2 highly expressed in NSCLC, esophageal squamous cancer, breast cancer, cholangiocarcinoma and pancreatic cancer, and can affect the migration ability of tumor cells and disease progression." (PMID 33648465, 2021). "ECM sclerosis has been shown to promote FERMT2 translocation to mitochondria and its interaction with pyrroline-5-carboxylate reductase 1 (PYCR1), which regulates crosstalk between the tumor and its microenvironment in breast cancer." (PMID 38352691, 2024). "Similarly, for early breast cancer, the best three k-gene discriminators are {GPR109B, PCOLCE2, PCSK5}, {PCSK5+COL10A1, FERMT2+SPINT2, MAOA+IGJ}, {COL1A1+PCSK5+TF, GPX3+COL1A1+SPINT2, GPX3+FAP+TMEM97}, and {RRM2+COL1A1+GPR109B+IGJ, RRM2+COL1A1+GPR109B+IGJ, RRM2+COL1A1+GPR109B+SPINT2}, respectively." (PMID 21060876, 2010).
esophageal squamous cell carcinoma (12 papers, 2015 to 2025). Esophageal squamous cell carcinoma (ESCC) is a type of esophageal carcinoma (EC) that can affect any part of the esophagus, but is usually located in the upper or middle third. "FERMT2 is a scaffolding protein that has been reported to promote the proliferation and migration of esophageal squamous cell carcinoma." (PMID 34195091, 2021).
hepatocellular carcinoma (12 papers, 2018 to 2025). A malignant tumor that arises from hepatocytes. "FERMT2, also known as Kindlin-2, has been associated with poor survival in lung adenocarcinoma and hepatocellular carcinoma and FERMT2 as well as other fermitin family members have been shown to promote EMT and metastasis through the ß catenin pathway." (PMID 36195845, 2022). "Fermitin family homolog 2 (FERMT2, also known as kindlin-2 or Mig-2), is a focal adhesion protein that is associated with increased metastatic potential of several types of cancers, including hepatocellular carcinoma, prostate cancer and gastric cancers 25-29." (PMID 32104508, 2020).
prostate carcinoma (10 papers, 2012 to 2022). A carcinoma that arises from epithelial cells of the prostate gland. "The floxed Fermt2 strain, therefore, provides a unique opportunity to investigate the role of Kindlin-2 in other cancer models such as the transgenic adenocarcinoma of the mouse prostate (TRAMP) model for prostate cancer." (PMID 35158908, 2022). "FERMT2 has been pinpointed as a biomarker for other cancers previously including non-small cell lung cancer and prostate cancer, but not for BCNHL." (PMID 36873459, 2022).
lung carcinoma (9 papers, 2012 to 2025). "Moreover, FERMT2 has been confirmed to function as a mechanosensor in human lung cancer tissues, where it interacts with the proline synthesis enzyme PYCR1 in response to alterations in ECM stiffness." (PMID 40119586, 2025). "In lung cancer, the expression pattern of FERMT2 in previous studies is controversial." (PMID 33934696, 2021). "FERMT2 together with FKBP3, SMAD9, GATA2, and ITIH4 was constructed as a prognostic signature of lung cancer based on the differential expression of immune genes." (PMID 36253873, 2022).
pancreatic cancer (9 papers, 2016 to 2024). "Analysis of the TCGA pancreatic cancer dataset revealed that FERMT2 was positively correlated with the TGF-β signaling pathway." (PMID 38910148, 2024). "Research has previously demonstrated that TGF-β1 upregulates FERMT2 expression in pancreatic cancer cells." (PMID 38910148, 2024). "The functional role of FERMT2 in pancreatic cancer was examined using gene set enrichment analysis (GSEA) with the TCGA dataset." (PMID 38910148, 2024). "After analyzing the Tumor Immune Single-cell Hub (TISCH) database, it was discovered that among the cell populations in pancreatic cancer, CAFs exhibited the highest FERMT2 expression, followed by cancer cells." (PMID 38910148, 2024). "Subsequently, FERMT2 promotes pancreatic cancer progression by downregulating HOXB9 and E-cadherin." (PMID 38910148, 2024). "The expression of FERMT2 was observed in pancreatic cancer tissues but not in healthy pancreatic tissues, as determined by tissue protein microarray analysis." (PMID 38910148, 2024). "Besides, the mRNA expression of FERMT2 positively correlated with ACTA2, COL1A1, FAP, and FSP based on TCGA pancreatic cancer data." (PMID 38910148, 2024).
Alzheimer disease (8 papers, 2016 to 2025). A progressive, neurodegenerative disease characterized by loss of function and death of nerve cells in several areas of the brain leading to loss of cognitive function such as memory and language. "Significantly, single nucleotide polymorphisms (SNPs) of FERMT2 are implicated in both familial Alzheimer's disease (fAD) and late‐onset Alzheimer's disease (LOAD), demonstrating the most pronounced association with stages of mild cognitive impairment." (PMID 40119586, 2025). "This approach highlighted the involvement of FERMT2 (or Kindlin-2), a genetic risk factor of Alzheimer’s disease (AD), as a potential key modulator of axon guidance, a neuronal process that depends on the regulation of APP metabolism." (PMID 33144711, 2021). "A recent meta-analysis of genome-wide association studies (GWAS) in population of Caucasian identified a single nucleotide polymorphism (SNP) rs17125944 in the FERMT2 gene as a new susceptibility locus for late-onset Alzheimer's disease (LOAD)." (PMID 27244899, 2016). "In 2013, a meta-analysis of 74 046 samples reported by the International Genomics of Alzheimer's Disease Project (IGAP) firstly found the susceptibility loci rs17125944 in FERMT2 gene for LOAD." (PMID 27244899, 2016). "FERMT2 has been found to interact with integrins to regulate many physiopathological processes; most notably, FERMT2 has been identified as being associated with amyloid precursor protein (APP) metabolism, which is a significant risk factor for Alzheimer's disease (AD)." (PMID 38352691, 2024).
gastric cancer (8 papers, 2014 to 2025). A primary or metastatic malignant neoplasm involving the stomach. "In various cancer types, including gastric cancer (GC), higher FERMT2 RNA expression was linked to poorer prognosis and increased hazard ratios (P = 2.3e-3)." (PMID 40024947, 2025). "In gastric cancer (GC), the fermitin family homolog-2 (FERMT2) is involved in macrophage signaling, promoting migration and invasion." (PMID 38352691, 2024). "High FERMT2 expression positively correlated with the abundance of nonparenchymal cells in gastric cancer TME, which limited the efficacy of immunotherapy by shaping the immunosuppressive microenvironment." (PMID 38352691, 2024).
colorectal cancer (7 papers, 2016 to 2024). A primary or metastatic malignant neoplasm that affects the colon or rectum. "FERMT2 has been found to be implicated in tumor pathogenesis and is highly expressed in a variety of cancers, including breast and colorectal cancers." (PMID 38352691, 2024). "On the other hand, FERMT2 has been identified as a novel oncogene that is highly expressed tumors, including breast, pancreatic, and colorectal cancers, and promotes invasion and metastasis." (PMID 38352691, 2024). "In this study, we firstly analyzed the expression of FERMT2 protein using the public database, and then we have verified the results in patients with colorectal cancer from our cohort, as well as in colorectal cancer cells." (PMID 36480537, 2022). "It is indicated that the expression of FERMT2 at mRNA level in colon carcinoma, colon adenocarcinoma, colorectal carcinoma and colon carcinoma epithelia were increased significantly than that of control tissues from several datasets." (PMID 36480537, 2022). "Whether the Alzheimer’s genetic risk factor, named as fermitin family homolog-2 (FERMT2), plays a pivotal part in the progressive process of colorectal carcinoma (CRC) yet remains unclear." (PMID 36480537, 2022). "Although the results of FERMT2 expression in colorectal cancers are inconsistent from different databases, and the reasons may be related to pathological classification, progress, patient population, detection window and other factors." (PMID 36480537, 2022). "For instance, FERMT2 severs as a tumor-promoting role in gastric cancer, pancreatic cancer and breast cancer, but as a tumor-suppressive role in epithelial ovarian cancer and colorectal cancer." (PMID 33934696, 2021). "In addition, studies have shown that FERMT2 can down-regulate and inhibit tumor cell functions in epithelial ovarian cancer, colorectal cancer and mesenchymal cancer cell." (PMID 33934696, 2021).
lung adenocarcinoma (6 papers, 2019 to 2024). A carcinoma that arises from the lung and is characterized by the presence of malignant glandular epithelial cells. "In order to verify the clinical value of the model, we finally examined the expression of FERMT2, FKBP3, SMAD9, GATA2 and ITIH4 in 30 lung adenocarcinoma tissues by immunohistochemistry, considering the availability of antibodies." (PMID 33648465, 2021).
melanoma (6 papers, 2019 to 2025). A malignant, usually aggressive tumor composed of atypical, neoplastic melanocytes. "In melanoma, the expression level of FERMT2 was identified to be associated with the efficacy of target therapies." (PMID 38352691, 2024). "Over-expression of FERMT2 was previously found to promote melanoma growth and migration, which was attributed to stimulate the downstream MAPK pathway, and was reported to be a potential therapeutic target for treating melanoma." (PMID 34771544, 2021). "For several genes, a role in melanoma progression has been reported; FERMT2 for instance has been found to impact melanoma metastasis." (PMID 32767816, 2021).
colon carcinoma (3 papers, 2022 to 2025). "When locations were compared, 2 signals were detected when comparing left and right colon cancers (the most significant genetic variant was located in the FERMT2 gene) and 3 when comparing rectal vs colon cancers (the most significant genetic variant was located in CNTNAP2 gene)." (PMID 36077729, 2022).
heart failure (3 papers, 2017 to 2021). Inability of the heart to pump blood at an adequate rate to meet tissue metabolic requirements. "Global deletion of the FERMT2 gene causes embryonic lethality and severe abnormalities of heart development, and genetic deletion of FERMT2 at late gestation or in adult cardiac myocytes results in heart failure and premature death because of enlargement of the heart and extensive fibrosis." (PMID 33125708, 2021).
cognitive deficits (2 papers, 2022 to 2024). "A recent study has shown that downregulation of Fermt2 in astrocytes can lead to reduction of territory size and associated cognitive deficits." (PMID 39528861, 2024). "FERMT2, a genetic risk factor for AD, has a link with brain amyloidosis in stage-dependent manner, which is most remarkable in the stage of mild cognitive impairment." (PMID 36480537, 2022).
aging (1 paper, 2017). A developmental process that is a deterioration and loss of function over time. "Moreover, the carriers with the TT genotype of FERMT2 rs4901317 and the GG genotype of SLC24A4 rs67063100 had a 0.23-fold increased risk for cognitive aging, compared to those with the CT genotype of FERMT2 rs4901317 and the A allele of SLC24A4 rs67063100." (PMID 28199971, 2017).
amyloidosis (1 paper, 2021). A disorder characterized by the localized or diffuse accumulation of amyloid protein in various anatomic sites. "The MMSE‐correlated DEPs were mainly involved in amyloidosis (DNM1, UBR1, OPTN, FERMT2), CNS disorder (WIPF1) and energy metabolism (COA6, COX7C, PDPR) processes." (PMID 34528736, 2021). "Specifically, the proteins involved in amyloidosis, including optineurin (OPTN), ras‐related protein Rab‐21 (Rab21), dynamin 1 (DNM1), peroxisomal bifunctional enzyme (EHHADH), fermitin family homolog 2 (FERMT2), E3 ubiquitin‐protein ligase UBR1 were increased in T2DM‐MCI compared with T2DM‐nMCI." (PMID 34528736, 2021).
esophageal cancer (1 paper, 2021). A primary or metastatic malignant neoplasm involving the esophagus. "Ectopic miR-544 and miR-338-5p could overcome DDP resistance of esophageal cancer via targeting and down-regulating oncogene E2F transcription factor 5 (E2F5) and fermitin family homolog 2 (FERMT2)." (PMID 34881242, 2021).
glaucoma (1 paper, 2023). Increased pressure in the eyeball due to obstruction of the outflow of aqueous humor. "Other GWAS studies have identified the FERMT2 SNP-risk allele associated with glaucoma, FERMT2 is a D3-PIP-binding protein." (PMID 37007713, 2023).
glioblastoma (1 paper, 2021). The most malignant astrocytic tumor (WHO grade IV). "Recent research has demonstrated that FERMT2 is overexpressed in many tumor types, including gastric, breast, kidney, glioblastoma, pancreatic, bladder, prostate, hepatocellular and esophageal cancer, and associated with tumor progression and poor prognosis." (PMID 33934696, 2021).
hereditary spastic paraplegia (1 paper, 2016). Hereditary spastic paraplegias (HSP) comprise a genetically and clinically heterogeneous group of neurodegenerative disorders characterized by progressive spasticity and hyperreflexia of the lower limbs. "Mutations in DDHD1 are found in patients with hereditary spastic paraplegia; CDKN3 is linked with different cancers while for FERMT2 and CNIH, no human diseases have been described." (PMID 27757173, 2016).
lipodystrophy (1 paper, 2021). A congenital or acquired disorder characterized by abnormal loss or redistribution of the adipose tissue in the body. "Despite that, transgenic mice with the deletion of FERMT2 in adipocytes possess severe lipodystrophy with drastically reduced adipose tissue mass." (PMID 34956370, 2021).